PRL (prolactin)
Diseases named in the same sentence as PRL in open-access papers (continued):
Sharing a sentence is not in itself a finding about the gene and the disease.
hypopituitarism (51 papers, 2010 to 2026). A condition of diminution or cessation of secretion of one or more hormones from the anterior pituitary gland. "The fact that hypopituitarism was observed only in hypoprolactinemia group, is indicating that more aggressive dissection for lowering prolactin level is potential risk of hypopituitarism." (PMID 39080760, 2024). "The etiologic distribution of hypopituitarism was found to be similar in PRL deficient and sufficient subjects." (PMID 38700812, 2024). "An expected parallelism related the severity of hypoprolactinemia to the extent of hypopituitarism, as hormone deficits were more frequently multiple in patients with severe PRL deficiency than in those with normal PRL (71% vs. 37%)." (PMID 39172174, 2024). "Combined deficiencies of growth hormone, thyrotropin, and prolactin are typical in congenital hypopituitarism, a form of hypopituitarism in which mutation in PIT1is a common genetic cause." (PMID 29992743, 2018). "Hypopituitary mutant dwarf mice with combined anterior pituitary hormone deficiencies of growth hormone, thyrotropin, and prolactin are valuable genetic models for the investigation of both congenital hypopituitarism and lifespan extension." (PMID 29992743, 2018). "As evidenced by Sheehan’s syndrome, stress at delivery, including postpartum hemorrhage, impairs the anterior lobe pituitary, which may impair milk production via decreased levels of prolactin caused by hypopituitarism." (PMID 29165138, 2017). "If this is well established in hypopituitarism as suggested by international Guidelines, the same management should be considered in isolated low PRL levels." (PMID 39172174, 2024). "Minimum yearly measurements of IGF1, PRL, cortisol, DHEAS, LH, FSH, testosterone or estradiol, FT4, and TSH are needed in brain-irradiated children since they are at risk to develop hypopituitarism over time." (PMID 39415786, 2024). "While the role of RT in inducing anterior pituitary deficiency has been extensively characterized, the role of low PRL level after RT as a potential predictor of the onset of hypopituitarism has been poorly investigated." (PMID 39172174, 2024). "POU1F1 also induces differentiation of GH-, PRL-, and TSHB-producing cell lineages in the anterior pituitary and, when mutated, causes multiple pituitary hormone deficiency syndrome and hypopituitarism." (PMID 37600690, 2023). "Significant risk factors in the univariable analysis included patients with EO, baseline PRL levels, hypopituitarism at diagnosis, presence of a macroprolactinoma, and cavernous sinus invasion." (PMID 36814862, 2023). "Of the 47 patients with a medically treated microprolactinoma, 39 (83.0%) were female, 20 (52.6%) had elevated prolactin levels, 13 (27.7%) had hypopituitarism, and 3 (6.4%) had adrenal insufficiency." (PMID 33025546, 2021). "The prevalence of hypopituitarism of almost all different axes (including the adrenal gland, thyroid gland, gonadal glands, prolactin, and neurohypophysis) in the evaluated patients exceeded 80%." (PMID 34603197, 2021). "Hypopituitarism was present in 49 patients (42.2%), adrenal insufficiency in 19 patients (16.4%), and 38 patients (32.8%) had persistently elevated prolactin levels at the time of study participation." (PMID 33025546, 2021). "Laboratory evaluation was notable for significantly elevated serum prolactin level (2,484 ng/mL, 2.6-13.2) and evidence of hypopituitarism." (PMID 34993034, 2021). "It has been suggested that severe PRL deficiency occurs late after all other anterior pituitary insufficiencies in the evolution of hypopituitarism and that very low levels of PRL are related to the severity of hypopituitarism." (PMID 27476159, 2016). "Hypogonadism occurs frequently in patients with acromegaly as a consequence of PRL and GH hypersecretion or hypopituitarism due to local mass effects." (PMID 25873948, 2015).
hypopituitarism (continued). "This possibility is supported by the fact that Pit1 mutations cause compound pituitary hormone deficiency (CPHD), in which expressions of the TSHβ gene as well as the prolactin (PRL) and growth hormone (GH) genes are decreased or abolished." (PMID 21533184, 2011). "The hypopituitarism displayed by Nestin-Cre mice is post-natal and specific to the Pit-1 lineage (GH, PRL and TSH cells)." (PMID 20625432, 2010). "These selective inclusion criteria, hence the low number of patients with normal PRL levels might influence the distribution of hypopituitarism etiologies." (PMID 38700812, 2024). "In a screening study in 509 patients with TBI or subarachnoid hemorrhage (SAH), set to determine the prevalence of post-traumatic hypopituitarism, PRL was measured in 93% and low PRL (defined as PRL < 2.8 ng/ml in females and < 2.1 ng/ml in males) was observed in 1 case, resulting in a 0.2% rate." (PMID 39172174, 2024). "Combined surgery and RT were found to be responsible for 10% of cases of hypopituitarism, and all patients receiving combined surgery and RT developed PRL deficiency determined by TRH stimulation test (PRL response < 18.6 ng/ml and < 41.6 ng/ml in males and females, respectively)." (PMID 39172174, 2024). "PRL is a neglected hormone in the diagnosis of hypopituitarism." (PMID 38700812, 2024). "Pathogenic variants within the gene encoding the pituitary-specific transcription factor, POU class 1 homeobox 1 (POU1F1), are associated with combined pituitary hormone deficiency (CPHD), including growth hormone, prolactin, and thyrotropin stimulating hormone deficiencies." (PMID 35456463, 2022). "Predictors of prolactin normalization and hypopituitarism improvement after surgery." (PMID 35154007, 2021). "Combined pituitary hormone deficiency (CPHD) is characterized by a deficiency of at least two of six anterior pituitary hormones, namely, growth hormone (GH), thyroid-stimulating hormone (TSH), prolactin (PRL), adrenocorticotropic hormone (ACTH), and at least one gonadotropin (LH, FSH)." (PMID 38147295, 2024). "We also found that lower prolactin levels at follow-up are correlated with anterior pituitary insufficiencies, supporting the idea that prolactin levels could be employed as a marker for hypopituitarism in long-term follow-up." (PMID 38274233, 2023). "Combined pituitary hormone deficiency (CPHD) is defined as deficiencies of growth hormone (GH), thyroid-stimulating hormone (TSH), the gonadotropins-luteinizing hormone (LH) and follicle-stimulating hormone (FSH), prolactin (PRL) and adrenocorticotropic hormone (ACTH)." (PMID 31948187, 2020). "Routine basal hormonal screening for TBI-induced hypopituitarism should include serum cortisol, free T3, free T4, TSH, IGF-1, FSH, LH, testosterone (in boys) or estradiol (in girls), prolactin, urine specific gravity, sodium, and plasma osmolality." (PMID 41300601, 2025). "Taking the limited availability of TRH into account, basal prolactin levels can be used in the first step and prevent unnecessary use of TRH stimulation test in most of the patients with hypopituitarism." (PMID 39037546, 2024). "In female patients prevalence of VFs was associated with the duration of the disease independently of the effects of hypopituitarism, age, BMD, serum PRL levels, and treatment with dopaminergic drugs." (PMID 25873948, 2015). "However, most studies on the effect of RT on pituitary function do not properly assess PRL secretion, as PRL deficiency is usually detected as part of hypopituitarism and not systematically investigated as an isolated disorder, which may lead to an underestimation of hypoprolactinemia after RT." (PMID 39172174, 2024). "Subsequent hormonal workup revealed an elevated prolactin level of 128.4 nanograms per milliliter (ng/mL) without evidence of additional hormonal co-secretion or hypopituitarism." (PMID 39050327, 2024).
hypopituitarism (continued). "She presented with no symptoms of hypopituitarism and her hormone panel only showed elevated prolactin, possibly due to her breastfeeding." (PMID 38326790, 2024). "A study investigating patients with multiple pituitary hormone deficiencies identified an independent effect of PRL on IGF-1 status through multiple regression analysis, though no direct correlation was found between actual PRL levels and IGF-1 levels in panhypopituitarism." (PMID 40370773, 2025). "Indeed, hypopituitarism is deemed being majorly responsible for the absence of sufficient release of growth hormone and prolactin to support normal body growth and lactation in DAT-KO mice." (PMID 32486390, 2020). "However, although metoclopramide may increase PRL levels, it is not a standardized method to evaluate PRL reserve in patients with hypopituitarism." (PMID 38700812, 2024).
autoimmune disease (49 papers, 2008 to 2025). A disorder resulting from loss of function or tissue destruction of an organ or multiple organs, arising from humoral or cellular immune responses of the individual to their own tissue constituents. "On the other hand, PRL has been associated with many autoimmune diseases, such as systemic lupus erythematosus (SLE), rheumatoid arthritis (RA), and multiple sclerosis (MS)." (PMID 40806464, 2025). "Clinical manifestations of autoimmune diseases have been associated with estrogens, prolactin (PRL), and growth hormone (GH) levels." (PMID 38680484, 2024). "Prolactin is another pro-inflammatory hormone implicated in development of autoimmune diseases due to its increased concentrations found in post-pubertal females compared to men." (PMID 31110493, 2019). "In conclusion, we define anti-PIT-1 antibody syndrome as a thymoma-associated autoimmune disease, which exhibits an acquired and specific GH, PRL, and TSH deficiency." (PMID 28216655, 2017). "Prolactin has an immunomodulatory effect and has been associated with B-cell-triggered autoimmune diseases, such as systemic lupus erythematosus (SLE)." (PMID 27314053, 2016). "The etiology and pathogenesis of gestational gigantomastia remain elusive, but many theories have been proposed, including excessive production of estrogen or prolactin, hormone receptor sensitivity, and underlying autoimmune disease triggered by pregnancy." (PMID 26713166, 2015). "In line with this, elevated PRL levels have been linked to autoimmune disorders such as systemic lupus erythematosus, systemic sclerosis, and RA." (PMID 25717285, 2015). "In this scenario, increased PRL levels would result in the maturation of B cell clones with self-reactivity and an increased risk for developing autoimmune diseases." (PMID 24454471, 2013). "Prolactin has an immunostimulatory effect and is associated with autoimmune diseases that are characterised by abnormal B cell activation, such as systemic lupus erythematosus (SLE)." (PMID 22404893, 2012). "Altered levels of PRL, which may favor either Th1 or Th2 dominance, are often linked to autoimmune diseases." (PMID 41476991, 2025). "High prolactin levels may result either in autoimmune disease presentation in mothers with predisposition or in flares in patients with existing conditions." (PMID 37447149, 2023). "PRL exerts a great influence in immune system modulation, mainly inhibiting the negative selection of autoreactive B lymphocytes and has been associated with the pathogenesis of several autoimmune disorders." (PMID 29483903, 2018). "In addition, prolactin has been linked to autoimmune disorder aggravation, which may account for the increased disease activity in females." (PMID 39449883, 2024). "PRL may prevent apoptosis of bone marrow immature B-cell clones that recognize self-antigens (potentially autoreactive clones), which may allow maturation of autoreactive B-cell clones, thus increasing the risk of developing autoimmune diseases." (PMID 27314053, 2016). "Our cases also included histories of pregnancy, elevated prolactin levels, treated latent tuberculosis, breast trauma, and autoimmune disorders, highlighting potential autoimmune, infectious, hormonal, and mechanical associations." (PMID 41255485, 2025). "This review summarizes current knowledge of the immunomodulatory effects of PRL in human viral infections and possibly its contribution to the development of autoimmune diseases." (PMID 41476991, 2025). "The authors argue that PRL primarily functions as a catalytic mechanism in the pathogenesis of autoimmune disorders, suggesting its role as an initial inflammatory instigator ({Ewerman, 2020 #378)." (PMID 41476991, 2025). "This review provides an overview of the current understanding of PRL’s immunomodulatory role in human viral infections and possibly its contribution to the development of autoimmune diseases." (PMID 41476991, 2025).
autoimmune disease (continued). "Increased levels of prolactin have been reported in various autoimmune diseases and were observed in the group of patients in this study, suggesting potential effects on the activation and secretion of cytokines in immune cells." (PMID 39791749, 2025). "The role of PRL has been described in many autoimmune diseases; however, few controlled analyses are available." (PMID 36833950, 2023). "Evidence suggests a relationship between prolactin and autoimmune diseases, in particular systematic lupus erythematosus (SLE), rheumatoid arthritis (RA), and peripartum cardiomyopathy (PPCM)." (PMID 37447149, 2023). "The higher frequency of autoimmune diseases in the female population compared to males suggests that certain hormones, such as prolactin (PRL), play a role in determining the prevalence of autoimmunity in women, particularly during childbearing age." (PMID 36389803, 2022). "In general, prolactin appears to enhance autoimmune diseases, and serum levels of prolactin are increased in some autoimmune diseases." (PMID 36518769, 2022). "In adult animals, PRL deprivation has repeatedly induced immunodeficiency and prevented the development of autoimmune diseases." (PMID 36389803, 2022). "In this regard, our results are not at odds with previous conclusions about the role of elevated prolactin in autoimmune disease since prolactin inhibits the immune-suppressive role of Tregs on T effector cell proliferation." (PMID 34375938, 2021). "For instance, some studies have shown that the PRL/cortisol ratio increased in autoimmune diseases such as systemic lupus erythematosus, rheumatoid arthritis, and Hashimoto’s disease." (PMID 34305584, 2021). "A study has reported alleviating effect of decreased level of prolactin in animal models of autoimmune diseases." (PMID 34746311, 2021). "In this review, we attempt to provide a critical overview of the link between PRL, autoimmune diseases, and motherhood." (PMID 29483903, 2018). "Although the interest on the relationship between PRL, immune modulation, and autoimmune diseases has emerged in the past few years, more studies are required to further delineate the influence of PRL in autoimmune disease." (PMID 29483903, 2018). "Increasing evidence involves elevated PRL levels in the pathogenesis of certain autoimmune diseases." (PMID 28966800, 2017). "While PRL has fundamental roles in reproduction and development, this pleiotropic hormone also contributes to autoimmune diseases and inflammation." (PMID 25717285, 2015). "Prolactin (PRL) has long been proposed as an immune-stimulating and detrimental factor in autoimmune disorders." (PMID 26236110, 2015). "Elevated serum PRL levels have been reported in several autoimmune diseases, including systemic lupus erythematosus (SLE)." (PMID 24454471, 2013). "Elevated serum levels of PRL have been reported in several autoimmune diseases, including multiple sclerosis and systemic lupus erythematosus (SLE), although this finding has not been reported for other diseases such as autoimmunity during chronic hepatitis C." (PMID 22404893, 2012). "Several studies have demonstrated a role for prolactin (PRL) and B cells in the development of autoimmune diseases such as systemic lupus erythematosus (SLE)." (PMID 22404893, 2012). "Future experiments should address the molecular role of PRL in this population and better define its contribution in autoimmune disease." (PMID 22404893, 2012). "Interestingly, the genes that encode PRL are located in the short arm of chromosome 6, in proximity to the HLA-DRB1 gene that is associated with autoimmune diseases, especially SLE." (PMID 40806464, 2025). "Research indicates that women typically have higher baseline PRL levels compared to men, which may contribute to the increased incidence of these autoimmune disorders in females." (PMID 41476991, 2025).